IL6 (interleukin 6)
Diseases named in the same sentence as IL6 in open-access papers (continued):
Sharing a sentence is not in itself a finding about the gene and the disease.
Pleural effusion (51 papers, 1998 to 2026). The presence of an excessive amount of fluid in the pleural cavity. "FER > 174.15 ng/mL, IL-6 > 25.47 pg/ml and pleural effusion were high risk factors for MPP with hypoxia." (PMID 32698769, 2020). "Ferritin> 174.15 ng/mL, IL-6 > 25.475 pg/ml and pleural effusion were related risk factors for hypoxia in MPP." (PMID 32698769, 2020). "Patients commonly exhibit fever, night sweats, weight loss, lymphadenopathy, ascites, pleural effusion, and hepatosplenomegaly, primarily via the action of IL-6." (PMID 31951598, 2020). "Multivariate logistic regression analysis revealed that ferritin> 174.15 ng/mL, IL-6 > 25.475 pg/ml, and pleural effusion were significantly associated with the incidence of hypoxia in MPP (P < 0.01)." (PMID 32698769, 2020). "IL-6 has been associated with the increment of vascular permeability, plasma leakage, pleural effusion, and ascites." (PMID 28827898, 2017). "IL-6 was also associated with pleural effusion and radiological appearance in MPP patients." (PMID 32393186, 2020). "The study established cutoffs with considerable predictive and diagnostic value for Tb with pleural effusions: 4000 pg/mL for IL-6 (sensitivity: 90.6%; specificity: 76.5%), 4 pg/mL for TNF-α (sensitivity: 90.6%; specificity: 79.4%), and 60 pg/mL for IFN-γ (sensitivity: 100%; specificity: 100%)." (PMID 28487810, 2017). "Another report, however, presents that the elevation of IL‐6 has been detected in 65% of patients presenting with ascites or pleural effusion." (PMID 41488232, 2026). "Bedside chest X-ray suggested progression of exudation and consolidation in both lungs, along with bilateral pleural effusion (and IL-6: 5938 pg./mL, CRP: 322 mg/L)." (PMID 41169424, 2025). "through multivariate logistic regression analysis, found that NLR, IL-6, CRP, LDH, D-dimer, pulmonary necrosis, pleural effusion, and pericardial effusion are all risk factors for embolism in children with RMPP." (PMID 40171163, 2025). "We performed a prospective observational study recruiting patients with pleural effusions secondary to infection and measured interleukin-6 in matched pleural fluid and serum (n = 76)." (PMID 40819633, 2025). "Our study further confirmed that elevated inflammatory markers such as CRP, LDH, neutrophils (%), IL-6, ESR, lung consolidation, combined pleural effusion were risk factors for RMPP." (PMID 40656195, 2025). "In this study, we also evaluated the availability of 12 serum cytokines within 48 h of symptom onset to predict AP patients with pleural effusion, and IL‐1β, IL‐6, IL‐8, and IL‐10 all showed good predictive value." (PMID 38411379, 2024). "A particularly notable example is Th17 cells, which correlated strongly negatively with the levels of IL-5, IL-6 and IL-8 in pleural effusion (r = -0.6, r = -0.7 and r = -0.7, respectively and p<0.05 for each)." (PMID 39737183, 2024). "The development of pleural effusions in animal #17012 was seen in two phases, which both came along with an increase in leukocyte numbers, IL-6 and troponin T levels." (PMID 39200391, 2024). "Alterations in cytokine profiles, including high tumor necrosis factor (TNF)-α, IL-6, and IL-1 levels and low interferon-γ levels, are common in both pleural effusion and RA." (PMID 39744302, 2024). "The rise in leukocytes, CRP and IL-6 indicates the occurrence of inflammatory processes coinciding with the development of the pleural effusions." (PMID 39200391, 2024). "In agreement with previous data, we found that IL-6 was present at high concentrations in the pleural effusion of MM and correlated with a worse prognosis." (PMID 34439164, 2021). "The levels of IL-6 were correlated inversely with abdominal pain (r = −0.880, p = 0.049) and the presence of pleural effusions (r = 0.710, p = 0.049)." (PMID 34576853, 2021). "We found that ferritin > 174.15 ng/mL, IL-6 > 25.47 pg/ml and pleural effusion were good predictors of MPP with hypoxia." (PMID 32698769, 2020).
Pleural effusion (continued). "Various researches had been performed concerning the levels of IL-6 which is the mediator and the regulator of inflammatory responses in pleural effusions due to miscellaneous diseases." (PMID 27034588, 2016). "Regarding early failure, significant and independent predictors were higher IL-6 levels on day 1 and pleural effusion, and for late failure, higher PCT levels on day 3, CURB 65 score ≥ 3, and multilobar involvement." (PMID 24996572, 2014). "Purified mononuclear cells from the pleural effusion of the patient were cultured in the presence of IL-6." (PMID 24330858, 2013). "Additionally, bilateral pleural effusion was noted, and the pneumonia had progressed compared with the previous state (and IL-6: 3557 pg./mL, CRP: 316 mg/L)." (PMID 41169424, 2025). "Early pre-clinical models explored the contribution of IL-6 in pleural effusions to constitutional MM symptoms, and cell line experiments suggested that anti-IFN-γ therapy could alleviate these symptoms." (PMID 38689325, 2024). "Furthermore, several single predictors have been suggested, like LDH, PCR, Ht, interleukin-6, BMI, pleural effusion, and triglyceride levels." (PMID 38610793, 2024). "Notably, IFN-γ, IL-6, and IL-8 were also significantly elevated in the pleural effusion, with IL-6 reaching 792.23 pg/ml (normal: 7.0 pg/ml)." (PMID 38162662, 2023). "Furthermore, it has been reported that pleural effusion and high leukocyte counts were highly correlated with IL-6 concentrations." (PMID 36971465, 2023). "Cytokine analysis showed elevated interleukin (IL) levels, especially IL-6 in pleural effusion." (PMID 38162662, 2023). "We found that smoking history, pleural effusion, number of treatment lines, acute phase proteins (IL-6 and CRP), CD8 + T lymphocyte count and serum alveolar epithelial proteins (including SP-A, SP-D and KL-6) were different between the CIP and non-CIP groups in the training cohort (P < 0.1)." (PMID 36050683, 2022). "The levels of PAI-1, IL-1β were higher and t-PA, IL-6 were lower in pleural effusions of the patients with tuberculous empyema and who must undergo operation than the patients who could be treated with closed drainage and anti-TB chemotheraphy." (PMID 27034588, 2016). "Moreover, among the examined factors, CCL1, CCL21 and IL-6 were markedly increased in pleural effusions from tuberculous pleurisy patients and the supernatants of cultured PFMCs after M.tb-specific antigen stimulation." (PMID 23028695, 2012). "Increased levels of IL-6 were observed in 65% of the patients who showed pleural effusion/ascites." (PMID 20090849, 2010). "These indicators included inflammatory factors and other features such as CRP, LDH, ESR, WBC, IL-6, neutrophil count (%), AST, ALT, duration of fever, lung consolidation, and pleural effusion." (PMID 40656195, 2025). "In the in vitro experiment, the combined inhibition of IL-6 and PD1 substantially enhanced the effector killing function of CD8+ T cells in NSCLC pleural effusion samples." (PMID 40040705, 2025). "IL-6, IL-8, IL-10, TNF (p<0.0001) levels were significantly higher in pleural effusion compared to plasma." (PMID 39737183, 2024). "Pleural effusion in systemic lupus erythematous (SLE) is a common symptom, and recent studies demonstrated that IL-6 has a pivotal role in its pathogenesis." (PMID 34530845, 2021). "The KMS-12 PE cell line which was established from the pleural effusion showed a very high level of CB2 receptor expression 98.4%, and the U-266 cell line which was reported to produce IL-6 showed a very high level 98.8%." (PMID 32471216, 2020). "Univariate analysis identified death related biomarkers, mainly including MIF levels, age, cavitary lesion, pleural effusion, drug-resistant, disseminated status and CRP, IL-6 and ALB." (PMID 30841876, 2019).
Pleural effusion (continued). "The concentration of cytokines (IL-6, TNFα, IFNɤ, MCP-1, IL-2) in pleural effusion were higher in mice in the BCG + SiCon group than in the PBS + SiCon group, which is consistent with previous studies." (PMID 30669315, 2019). "There are few reports about the IL-2, IL-6, and TNF-α levels in pleural effusions of patients with tuberculous pleurisy and tuberculous empyema." (PMID 27034588, 2016). "A final model to predict CAP failure includes higher IL-6 levels on day 1, CURB 65 score ≥ 3, pleural effusion and multilobar involvement." (PMID 24996572, 2014). "However, heterogeneity for LDH, WBC, IL-6, AST, ALT, Neutrophils (%), CRP, and Combined pleural effusion remained largely unchanged." (PMID 40656195, 2025). "Our case treated with sarilumab and a previous case treated with tocilizumab suggest the potential of IL-6 inhibitors to control both pleural effusion and joint activity, even without GCs." (PMID 39744302, 2024). "In contrast to the first phase of pleural effusions around day 30, there were also relevant increases in NT-proBNP, CK, CRP as well as several chemokines and pro-inflammatory cytokines, like MCP-1, I-TAC, MIG, IL-6, IL-12, TNF-α and eotaxin." (PMID 39200391, 2024). "Conforming with previous studies which mostly used peripheral blood samples, our pleural effusions study also confirmed the elevated levels of CA12, CD40, IL-6, IL-8, PD-L1, and VEGFA, proposing their potential either as biomarkers for severity and prognosis of the disease or targets for therapy." (PMID 36428847, 2022). "We aimed to examine whether the interleukin-1β (IL-1β), IL-2, IL-6, tumor necrosis factor-α (TNF-α), plasminogen activator inhibitor type-1 (PAI-1), and tissue plasminogen activator (t-PA) levels were different in pleural effusions of tuberculous pleurisy and tuberculous empyema." (PMID 27034588, 2016). "The aim is to examine whether the interleukin-1β (IL-1β), IL-2, IL-6, tumor necrosis factor-α (TNF-α), plasminogen activator inhibitor type-1 (PAI-1), and tissue plasminogen activator (t-PA) levels were different in pleural effusions of tuberculous pleurisy and tuberculous empyema." (PMID 27034588, 2016). "The results indicated that WBC AST, ALT, CRP, IL-6, ESR, the duration of fever, and pleural effusion showed no significant publication bias, while LDH, neutrophil percentage, and lung consolidation showed evidence of publication bias." (PMID 40656195, 2025).
prostate tumor (51 papers, 2007 to 2025). "IL-6 has been well studied for its multiple roles in cancer, it is produced by prostate tumor cells, tumor-associated macrophages (TAMs), CD4+ T cells, and fibroblasts." (PMID 33076397, 2020). "Human prostate tumors with IL-6 elevation and loss of ESE3/EHF were associated with STAT3 activation and displayed upregulation of genes related to cell adhesion, cancer stem-like and metastatic spread." (PMID 27732936, 2016). "Inspired by these findings, in this study, we aimed to address whether IL-6 has a causative role in de novo spontaneous prostate tumor initiation and thus generated prostate-specific IL-6 transgenic mouse lines." (PMID 28077171, 2017). "Decreased expression of the PR in cancer associated stroma may contribute to the elevated SDF-1 and IL-6 levels in prostate tumors and enhance prostate tumor progression." (PMID 24664419, 2014). "Previous studies reported that IL6/Jak/Stat3 pathways is operating at multiple levels during prostate tumor progression." (PMID 39865080, 2025). "In this study, we investigated the IL-6 signaling response to the inflammatory microenvironment of prostate tumors." (PMID 39452544, 2024). "Fexofenadine, an H1 receptor blocker, suppressed the expression of inflammatory cytokines, such as Il-6, IL-10, IL-4, and IL-17, and reduced infiltration of MDSCs into prostate tumors." (PMID 36900168, 2023). "Microarray-based gene expression analysis of larger sample sizes has shown increased expression of proinflammatory cytokines, including IFN-γ, TNF-α and interleukins (IL-1β, IL-6, and IL-8) in prostate tumor tissues of AA men than CAs14,22." (PMID 37698493, 2023). "High-fat diets (HFD) promote local inflammation in prostate tumors which leads to the increased secretion of inflammatory cytokines, such as IL-6 that culminates into increased recruitment and infiltration of myeloid-derived suppressor cells (MDSCs)." (PMID 36900168, 2023). "As a direct target gene of CHD1, IL-6 mediates the recruitment and activation of MDSCs in prostate tumors." (PMID 36776288, 2023). "Our results demonstrated that IL-6 induction in prostate tumor spheres upregulates NANOG gene expression." (PMID 37987305, 2023). "Because IL-6 is a cytokine produced by many cell types in inflamed prostate tissue, numerous studies suggest a direct link between chronic inflammation and prostatic tumor development." (PMID 35464825, 2022). "HFD can induce prostate tumor growth through a large suite of chemical signaling pathways, such as the activation of IL6/pSTAT3 or MCP-1/CCR2 signalings, or through the inhibition of tumor suppressor gene PTEN." (PMID 31011360, 2019). "As a pro-inflammatory cytokine, interleukin-6 (IL-6) is expressed in both of prostate tumors and the stromal tumor microenvironment." (PMID 32039001, 2019). "It has been found that prostate tumor cells produce large amounts of IL-6 and express its receptors, IL-6R (gp80) and gp130, allowing them to respond in an autocrine manner to IL-6." (PMID 30134795, 2018). "These enhanced levels of AIRE modulate the prostate tumor microenvironment by transcriptionally activating a malignancy gene IL-6 in androgen-independent cells." (PMID 29795364, 2018). "We compared the prostate pathology, tumorigenic signaling components, and prostate tumor microenvironment of the IL-6 transgenic mice with wild type littermates." (PMID 28077171, 2017). "It is also interesting to note that in vivo studies in animals and human clinical trials have been conducted with anti-IL-6 monoclonal antibodies to target prostate tumor." (PMID 28356100, 2017). "IL-6, a cytokine which is elevated in prostate tumors, reduced the expression of PCAT29 in both DU145 and LNCaP cells by activating signal transducer and activator of transcription 3 (STAT3)." (PMID 28467474, 2017). "We also observed autocrine IL-6 induction in mouse prostate tumor cell lines exposed to exogenous IL-6." (PMID 28077171, 2017).
prostate tumor (continued). "This analysis revealed that the IL-6high/ESE3low tumors were significantly enriched of genes attenuated in IL-6 deprivation (Croonquist_IL-6_DN), underlying the accuracy of our approach in extracting relevant IL-6 targets in prostate tumors." (PMID 27732936, 2016). "In vivo, IL-6 inhibition significantly prolonged the delay in prostate tumor growth after irradiation." (PMID 23806095, 2013). "Our studies suggest that let-7c suppresses prostate tumor growth by several pathways including regulation of IL-6, Myc, Lin28 and the AR." (PMID 22479342, 2012). "The interplay between inflammation, immunity, and tumor microenvironment in prostate tumors demonstrates that IL-6 production might influence tumor growth." (PMID 39452544, 2024). "Also, in the current paper, we observed that IL-6 modulates acute phase reaction markers and oxidative stress-related parameters in prostate tumors." (PMID 39452544, 2024). "Inducing IL-6 in prostate tumor spheres stimulates stemness biomarker NANOG genes." (PMID 37987305, 2023). "Both DU-145 spheres and IL-6-induced prostate tumor spheres were successfully generated." (PMID 37987305, 2023). "A number of recent findings support the central role of IL-6 in prostate tumor pathology." (PMID 35464825, 2022). "Indeed, it was demonstrated in a prostate-specific IL-6 transgenic mice that IL-6 autonomously induces prostate neoplasm secondary to the activation of STAT3/IGF signaling." (PMID 35406450, 2022). "Immunotherapy focused on IL-6 involvement in prostate tumor could help the urologists and oncologists for a better management of the patients with prostatic tumors." (PMID 35464825, 2022). "Interleukin-6 (IL-6) proved to be involved in the prostate tumor pathogenesis." (PMID 35464825, 2022). "Because IL-6 is a cytokine produced by many cell types in the inflamed hyperpasic prostatic tissue, a lot of studies suggested a direct link between inflammation and prostatic tumors." (PMID 35464825, 2022). "And studies have found that in mice bearing TC1 murine prostate tumors, whether they were treated with antiandrogen therapy or silencing of AR, the expression of IL-6 and STAT3 in mouse tumors would increase." (PMID 33995485, 2021). "Furthermore, IHC data on 167 clinical prostate specimens demonstrated a positive correlation between CD44 and IL-6 levels in prostate tumor specimens." (PMID 31315262, 2019). "The activation of NF-κB controls the expression of numerous proinflammatory genes, including interleukin 6 (IL-6), that is highly expressed in most prostate tumors and regulates key functions, such as proliferation, apoptosis, angiogenesis, and differentiation." (PMID 30646518, 2019). "With this model, we demonstrate that IL-6 induces prostate neoplasm autonomously." (PMID 28077171, 2017). "In addition, it was reported that elevated ROS produced by prostate tumor initiating cells was required for the activation of IL-6/STAT3, which was related with carcinogenesis of human prostate cells." (PMID 28947972, 2017). "ESE3/EHF and IL-6 were significantly inversely correlated in prostate tumors." (PMID 27732936, 2016). "IL-6/STAT3 is involved in the communications between prostate tumor cells and the microenvironment." (PMID 27611945, 2016). "Besides NF-κB dependent interleukin 6 pathway not only support prostate tumor survival and prevent apoptotic event but also activate AR during emergence of androgen independent PCa." (PMID 26295410, 2015). "IL-6 production, however, was differentially regulated by LPS stimulation in prostate tumor cells." (PMID 24966802, 2014). "Furthermore, it has been shown that BMP6 secreted from prostate tumor cells acts directly upon macrophages to stimulate secretion of IL-6, which ultimately results in neuroendocrine differentiation of the tumor." (PMID 23840733, 2013). "Observations of the clinical behaviour of prostate tumors suggest that the increased secretion of IL-6 and CCL5 and the higher expression of PSMA may be correlated." (PMID 19242540, 2009).